SOX11 (SRY-box transcription factor 11)
Diseases named in the same sentence as SOX11 in open-access papers (continued):
Sharing a sentence is not in itself a finding about the gene and the disease.
glaucoma (6 papers, 2017 to 2025). Increased pressure in the eyeball due to obstruction of the outflow of aqueous humor. "Taking aniridia as an example, whilst PAX6 mutations remain the predominant cause, variants in CYP1B1, FOXC1, PXDN and SOX11 have also been reported in patients with childhood glaucoma and aniridia." (PMID 41011222, 2025). "We therefore also examined Sox11 and Bdnf mRNA isoform levels in different stages of glaucoma, a blinding disease associated with chronic degeneration of RGCs and optic nerve axons." (PMID 29209164, 2017). "In animals with severe glaucoma, the level of Sox11 decreased to near control levels." (PMID 30619460, 2018). "In order to test whether this was the case for Sox11 and Bdnf, we examined their mRNA levels at different stages of glaucoma, the most common neurodegenerative disease." (PMID 29209164, 2017). "Interestingly, there was a significant and steady increase in levels of Sox11 long 3′UTR message in moderate up to more than twofold in severe glaucoma stages (p = 0.0012)." (PMID 29209164, 2017). "In secondary childhood glaucoma cases, alterations in CYP1B1 (25%), SOX11 (13%), FOXC1 (13%), GJA8 (13%) and LTBP2 (13%) were detected." (PMID 35011756, 2021). "Furthermore, two isoforms of Sox11 with different 3′UTR lengths are present in the retina, and the long isoform is specifically upregulated in later stages of glaucoma." (PMID 29209164, 2017).
lymphoid neoplasm (6 papers, 2010 to 2024). A neoplasm composed of a lymphocytic cell population which is usually malignant (clonal) by molecular genetic and/or immunophenotypic analysis. "Vegliante found that SOX11 expression is related to methylation of SOX11 gene promoter in lymphoid neoplasms." (PMID 24188789, 2013). "In lymphoid neoplasms, SOX11 shows high expression levels in B-ALLs with the TEL-AML1 fusion or E2A rearrangement as well as in the great majority of cases of MCL." (PMID 21738649, 2011). "To elucidate the molecular mechanisms leading to such deregulation, we performed a comprehensive SOX11 gene expression and epigenetic study in stem cells, normal hematopoietic cells and different lymphoid neoplasms." (PMID 21738649, 2011). "In conclusion, our data provide a comprehensive characterization of the epigenetic mechanisms leading to SOX11 deregulation in lymphoid neoplasms." (PMID 21738649, 2011). "In our series, although SOX11 was silenced in all cases showing methylation, a wide range of samples, from normal cells to lymphoid neoplasms, were also silenced in spite of an unmethylated status of the SOX11 promoter." (PMID 21738649, 2011). "In order to gain further insights into SOX11 expression patterns observed in stem cells, normal hematopoietic cells and lymphoid neoplasms, we performed qPCR-ChIP experiments with antibodies against activating and silencing histone modifications." (PMID 21738649, 2011). "Several studies have recently demonstrated that SOX11 is up-regulated in various aggressive lymphoid neoplasms." (PMID 21738649, 2011). "A very similar enrichment pattern as in NTERA-2 was observed in lymphoid neoplasms expressing SOX11." (PMID 21738649, 2011). "In lymphoid neoplasms, SOX11 was highly expressed in TEL-AML1-positive ALL (cell line REH) as well as in all MCLs studied, including eight cell lines and seven primary cases." (PMID 21738649, 2011). "At the mechanistic level, additional studies are required to elucidate which is the functional role of the illegitimate SOX11 expression in lymphoid neoplasms, and which upstream transcription factors and histone modifying enzymes are involved in this phenomenon." (PMID 21738649, 2011). "Epigenetic changes like DNA methylation and histone modifications, that regulate gene expression without changing the DNA sequence, could be involved in deregulating SOX11 expression in lymphoid neoplasms." (PMID 21738649, 2011). "Thus, based on both experimental and previous clinical observations we suggest that SOX11 can act as a master regulator of lymphoid tumor cell growth." (PMID 20624318, 2010). "Thus, it is likely to hypothesize that genetic or epigenetic changes affecting SOX11 regulators take place in lymphoid neoplasms and result in aberrant de novo SOX11 expression." (PMID 21738649, 2011). "SOX-11 mRNA and nuclear protein expression are seen in nearly all cyclin D1 positive and negative MCLs, but not in other mature lymphoid neoplasms or in normal lymphocytes." (PMID 39258061, 2024). "In contrast, adult stem cells, normal hematopoietic cells and other lymphoid neoplasms do not express SOX11." (PMID 21738649, 2011). "The SOX11 promoter of non-malignant cells was consistently unmethylated whereas lymphoid neoplasms with silenced SOX11 tended to acquire DNA hypermethylation." (PMID 21738649, 2011). "In some lymphoid neoplasms without SOX11 expression, this gene acquires variable degrees of DNA methylation." (PMID 21738649, 2011).
coloboma (5 papers, 2013 to 2023). An abnormality in which a part of a structure in one or both eyes is missing. "We screened DNA samples from 79 patients with microphthalmia, anophthalmia, or coloboma (MAC) and identified two novel heterozygous SOX11 variants in individuals with coloboma." (PMID 25010521, 2014). "We also provide evidence that SOX11 dosage changes or mutations contribute to human coloboma, microphthalmia, and rod photoreceptor dysfunction." (PMID 25010521, 2014). "Taken together, these data demonstrate that perturbed SOX11 function, either through mutation or decreased gene dosage, contributes to structural (microphthalmia/coloboma) or functional (rod photoreceptor) phenotypes." (PMID 25010521, 2014). "Moreover, Sox4- and Sox11-deficient animal models display coloboma, cardiac malformations and brain defects like those seen in CHARGE syndrome." (PMID 36172288, 2022). "Thus, our work establishes a novel link between Sox11 and Hh signaling, and suggests that mutations in SOX11 contribute to pediatric eye disorders such as coloboma." (PMID 25010521, 2014). "To determine whether changes in mitotic activity underlie the lens and coloboma phenotypes in sox11 morphants, we immunolabeled retinal sections from control and sox11 morphants with an antibody to phosphohistone H3 (PH3)." (PMID 25010521, 2014). "Sox11-deficient zebrafish embryos displayed delayed and abnormal lens formation, coloboma, and a specific reduction in rod photoreceptors, all of which could be rescued by treatment with the Hedgehog pathway inhibitor cyclopamine." (PMID 25010521, 2014). "Sox11−/− mice exhibit ocular abnormalities such as anterior segment dysgenesis, microphthalmia, a persistent lens stalk, delayed lens formation, and coloboma." (PMID 25010521, 2014). "Our work, in combination with previous studies, strongly supports a contribution from SOX11 to coloboma phenotypes, however our data indicate that the relationship is complex." (PMID 25010521, 2014). "The prevalence of ocular phenotypes was significantly reduced in the double morphants (sox11 MO: 70.3%±6.7% malformed lens, 75.4%±8.3% coloboma; sox11 + shha MOs: 28.9%±9.2% malformed lens; 34.7%±2.7% coloboma; p<0.0001)." (PMID 25010521, 2014). "We then injected sox4 mRNA into sox11 morphants and found that this significantly reduced the proportion of embryos with lens and coloboma phenotypes." (PMID 25010521, 2014). "The proportion of embryos displaying a malformed lens at 24 hpf (21.3±8.8%) or coloboma at 2 dpf (10.1±3.8%) was significantly reduced after cyclopamine treatment, compared to vehicle-treated sox11 morphants (>70% for both phenotypes; p<0.0001)." (PMID 25010521, 2014). "Approximately 54% (15 of 28 individuals examined) of sox11 morphant retinas with coloboma also exhibited poor or reduced retinal lamination, suggesting a delay in retinal differentiation." (PMID 25010521, 2014). "The coloboma phenotype of sox11 morphants is similar to the zebrafish blowout mutant, in which increased Hedgehog signaling results in altered proximodistal patterning of the optic vesicle." (PMID 25010521, 2014). "Sox11 morphant lenses mostly recovered to a spherical shape by 2 days post fertilization (dpf), however at this stage a similar proportion of morphants (70.0±7.7%) displayed coloboma." (PMID 25010521, 2014). "Interestingly, we found that expression of all three rod lineage genes was qualitatively normal in sox11 morphant retinas, even those with coloboma and poor lamination." (PMID 25010521, 2014). "Consistent with this hypothesis, we observed a significantly greater proportion of embryos with coloboma in sox4/sox11 double morphants than when either gene was knocked down alone (data not shown)." (PMID 25010521, 2014). "To test this hypothesis, we injected bmp7b mRNA into control and sox11 morphant embryos, and determined the proportion of embryos that displayed lens defects and coloboma at 24 hpf and 2 dpf, respectively." (PMID 25010521, 2014).
coloboma (continued). "In contrast to wild type human SOX11 mRNA, mRNA containing either variant failed to rescue the lens and coloboma phenotypes of Sox11-deficient zebrafish, and both exhibited significantly reduced transactivation ability in a luciferase reporter assay." (PMID 25010521, 2014). "This suggests that similar mechanisms may underlie the ocular morphogenesis and retinal developmental defects observed in sox11 morphants with coloboma." (PMID 25010521, 2014). "Indeed, we found that bmp7b expression was significantly reduced in sox11 morphants, and that injection of bmp7b mRNA into sox11 morphants could rescue the lens and coloboma phenotypes." (PMID 25010521, 2014). "In addition, our group has previously shown that Sox11 contributes to coloboma in zebrafish and humans and another group has identified an individual with CHARGE with a chromosomal duplication involving the SOX11 locus." (PMID 36172288, 2022). "Although the phenotypes of zebrafish blowout (blw) mutants and sox11 morphants are similar with respect to coloboma, blw mutants do not appear to have a defect in the differentiation of rod photoreceptors or any other retinal cell types." (PMID 25010521, 2014). "In contrast, of the sox11 morphant retinas that did not display coloboma, only 14% were poorly laminated (4 of 29)." (PMID 25010521, 2014). "Since we found that a significant proportion of sox11 morphant retinas with coloboma also displayed poor lamination, indicating a potential delay in retinal development, for analysis we divided the sox11 morphants into those with and without coloboma." (PMID 25010521, 2014). "In Sox11−/− mutant embryos, the OC fails to close, resulting in a coloboma, a folded retina and a small lens that remains attached to the cornea." (PMID 23516376, 2013). "We show that in the absence of Sox11, levels of the Sonic Hedgehog (Shh) ligand are greatly elevated, which disrupts the proper patterning of the optic stalk and optic vesicle, resulting in coloboma." (PMID 25010521, 2014). "Whereas wild type SOX11 mRNA significantly reduced the proportion of sox11 morphants displaying lens defects and coloboma, no significant rescue was observed with mRNA containing either SOX11 variant, suggesting that both sequence changes compromise SOX11 function." (PMID 25010521, 2014).
diffuse large B-cell lymphoma (5 papers, 2011 to 2023). "Rare cases of diffuse large B-cell lymphomas could be positive for cyclin D1, but they frequently lack CCND1 gene translocation and lack immunoreactivity for SOX-11." (PMID 34442137, 2021). "In contrast, patients with an indolent variant of MCL and other mature B-cell neoplasias such as chronic lymphocytic leukemia (CLL), follicular lymphoma (FL) or diffuse large B-cell lymphoma (DLBCL) do not express SOX11." (PMID 21738649, 2011).
hypogonadotropic hypogonadism (5 papers, 2022 to 2025). Abnormal ovarian or testicular function due to insufficient hormonal stimulation from the hypothalamic-pituitary axis. "Thirdly, nearly one in five of the SOX11 mutant patients had hypogonadotrophic hypogonadism which was rare reported in CSS patients." (PMID 35938035, 2022). "In addition, ocular malformations (oculomotor apraxia, coloboma, and microphthalmia) and hypogonadotropic hypogonadism were also reported in patients with SOX11 variation." (PMID 35938035, 2022).
breast tumors (4 papers, 2013 to 2021). "Our results suggest that SOX11 may be a potential biomarker for breast tumours with elevated risk of developing metastases and may require more aggressive therapies." (PMID 32909943, 2020). "Using methylation and expression data from normal breast samples and breast tumors collected in TCGA, we found that while SOX11 expression is kept low in normal breast samples, CpG sites near SOX11 are not highly methylated." (PMID 26894864, 2016). "Besides genes that are hypermethylated only in breast tumors (compare with breast normals), users can also find genes that are hypermethylated only in endometrial tumors (compare with endometrial normals) (such as CCDC81), and in both tumors (such as SOX11)." (PMID 23630576, 2013).
endometrial carcinoma (4 papers, 2022 to 2023). A malignant tumor arising from the epithelium that lines the cavity of the uterine body. "It has been reported that SOX11 hypermethylation is closely associated with MSI in endometrial cancer." (PMID 36551589, 2022). "Recent studies also point out that miR-145-5p inhibits cell proliferation and induces cell apoptosis in the bladder and endometrial cancer cells by targeting SOX11." (PMID 35368699, 2022).
follicular lymphoma (4 papers, 2010 to 2025). Follicular lymphoma is a form of non-Hodgkin lymphoma characterized by a proliferation of B cells whose nodular structure of follicular architecture is preserved. "The follicular lymphoma cell line did not express any SOX11 and no change in proliferation was consequently detected (data not shown)." (PMID 20624318, 2010).
hypertrichosis (4 papers, 2023 to 2025). Excessive hair growth anywhere on the body. "Initially, this syndrome was classified under the umbrella of CSS, similarly to SOX11-neurodevelopmental disorder, but both conditions lacked the most specific features of CSS (e.g., fifth-finger nail hypoplasia, corpus callosum agenesis, and hypertrichosis and hirsutism)." (PMID 38397148, 2024).
lymph node metastasis (4 papers, 2013 to 2021). "None of the other clinical‐pathological parameters analyzed, including lymph node metastasis, tumor size, Her‐2 or Ki‐67, were significantly related to SOX11 expression (p > .05)." (PMID 32043610, 2020). "It is noteworthy that SOX11 is a correlated with longer survival in patients with lymph node metastasis and deep tumor invasion, suggesting that SOX11 is a predictor of patient survival even in advanced stage." (PMID 24604109, 2014). "However, the methylation rate of the SOX11 gene promoter in the nasopharyngeal carcinoma tissues from patients with lymph node metastasis is significantly higher than nasopharyngeal carcinoma tissues from patients without lymph node metastasis." (PMID 24188789, 2013). "As SOX10 correlates with the rate of lymph node metastasis, a double positivity of MMs for SOX10/SOX11 might be used as an indicator of the presence of tumor cells in lymphatic and systemic circulation." (PMID 33801642, 2021). "In 116 patients with lymph node metastasis, 55 cases (47.4%) were SOX11-positive and 61 cases (52.6%) were SOX11-negative." (PMID 24604109, 2014). "SOX11 was not significantly correlated with survival in patients without lymph node metastasis (left) and at early tumor invasion stage (T1+T2) (left)." (PMID 24604109, 2014). "Of note, the SOX11 positive percentile was higher in lymph node metastasis negative and stage (T1+T2) tumors than lymph node metastasis positive and stage (T3+T4) tumors, although this was not statistically significant." (PMID 24604109, 2014).
lymphoblastic lymphoma (4 papers, 2016 to 2025). A lymphoma composed of immature small to medium-sized precursor lymphoid cells (lymphoblasts). "Few cases of DLBCL can express cyclin D1(2%), but they are negative for SOX11.2,19 Lymphoblastic lymphomas must be ruled out because of their close resemblance to the blastoid cells of B-MCL." (PMID 39099606, 2024).